GLO1 (glyoxalase I)
Diseases named in the same sentence as GLO1 in open-access papers (continued):
Sharing a sentence is not in itself a finding about the gene and the disease.
diabetic cardiomyopathy (3 papers, 2019 to 2020). Diabetic cardiomyopathy is a disorder of the heart muscle in people with diabetes. "Accumulation of methylglyoxal (MG) arising from downregulation of its primary degrading enzyme glyoxalase-1 (Glo1) is an underlying cause of diabetic cardiomyopathy (DC)." (PMID 32640624, 2020). "In emerging studies, GLO1 has been implicated in diabetic cardiomyopathy, coronary artery disease (CAD), and myocardial infarction." (PMID 31792287, 2019).
fatty liver (3 papers, 2018 to 2024). "Separately, hepatic GLO1 expression was decreased in a murine model of hyperhomocysteinemia-induced fatty liver." (PMID 29456458, 2018). "Accordingly, ST-I4C may reduce AGE accumulation and RAGE expression to improve hepatic steatosis by increasing Glo-1 expression in response to MGO exposure." (PMID 31438528, 2019). "Therefore, Glo1 activity could serve as a prognostic marker for the early detection of fatty liver disease." (PMID 38668337, 2024).
fibrosarcoma (3 papers, 2015 to 2022). A malignant mesenchymal fibroblastic neoplasm affecting the soft tissue and bone. "It was shown by Wang and co-workers that overexpression and nuclear translocation of GLO1 might be associated with tumor progression in murine fibrosarcoma." (PMID 26287160, 2015).
glioblastoma (3 papers, 2018 to 2025). The most malignant astrocytic tumor (WHO grade IV). "Inhibition of GLO1 in cancers that up-regulate glycolysis has been proposed as a therapeutic targeting strategy, but this approach has not been evaluated for glioblastoma multiforme (GBM), the most aggressive and difficult to treat malignancy of the brain." (PMID 29385725, 2018).
glioma (3 papers, 2010 to 2022). A benign or malignant brain and spinal cord tumor that arises from glial cells (astrocytes, oligodendrocytes, ependymal cells). "Overexpression of GLO1 in glioma cell lines was associated with tumor cell proliferation, migration, and invasion." (PMID 35877430, 2022). "Analysis of All glioma tumors highlighted two genes involved in pyruvate metabolism that were associated with IDH1; these were glyoxalase I (GLO1) and pyruvate carboxylase (PC)." (PMID 35877430, 2022). "As a result of increased intracellular accumulation of MG in U87 and T98 gliomas following GLO1 inhibition by a small molecule inhibitor or short hairpin RNAs (shRNAs), we observed increased levels of DNA-AGEs in genomic DNA as measured by LC-MS/MS." (PMID 29385725, 2018). "Comparison of GLO-1 expression in the commercially available glioma cell lines U-87, A-172, U-251, and U-373 was assayed by Western blot, yielding a band corresponding to the expected size of 23 kD." (PMID 20454582, 2010). "The results of our experiments suggest that TRG, in addition to other drugs which inhibit the activity of GLO-1, should be looked at further for use in glioma therapy." (PMID 20454582, 2010). "To test this idea, we assayed GLO-1 protein levels in four select glioma cell lines in order to find one that demonstrated robust expression." (PMID 20454582, 2010). "Although the prognostic implication was not consistently observed across all datasets, the results suggest that GLO1 overexpression may contribute to worse clinical outcomes in certain high-grade glioma cases." (PMID 29385725, 2018). "This decrease in glyoxalase I protein may be one mechanism by which this potentiation occurs, and troglitazone may be a candidate for use in glioma therapy." (PMID 20454582, 2010). "Our data demonstrates that TRG may have future clinical potential in enhancing the effects of chemotherapeutic agents against glioma, and one probable mechanism by which this occurs is through decreasing GLO-1 expression." (PMID 20454582, 2010). "Targeting GLO1 with shRNA similarly increased CEdG levels and RAGE expression, and was cytotoxic to glioma cells." (PMID 29385725, 2018). "To evaluate GLO1 in GBM, we examined data from The Cancer Genome Atlas (TCGA) and performed gene and protein expression analyses from surgical GBM specimens and glioma cell lines (U87, T98)." (PMID 29385725, 2018). "Because of the association of lower GLO-1 expression in oligodendrogliomas with chromosome 1p losses, and the notable role of this enzyme in cancer chemoresistance, decreasing expression of GLO-1 in gliomas expressing it at high levels may make them more susceptible to chemotherapy." (PMID 20454582, 2010).
ischemia (3 papers, 2014 to 2020). A hypoperfusion of the BLOOD through an organ or tissue caused by a PATHOLOGIC CONSTRICTION or obstruction of its BLOOD VESSELS, or an absence of BLOOD CIRCULATION. "To further validate the restored angiogenic capacity of D‐ADSCs through GLO1 overexpression, we established a diabetic hindlimb ischemia mice model and intramuscularly injected the ischemic hindlimbs with PBS, D‐ADSCs, G‐D‐ADSCs, or ND‐ADSCs (5 × 106 cells, 100 μL; n = 6) postoperatively." (PMID 28170200, 2017). "At 75 min after the onset of ischemia a clear endothelial localization on contra- and ipsilateral sites with a higher intensity on ipsilateral site was detected in sections stained for laminin, Glo1 and DAPI endothelium of blood vessels showed." (PMID 24498315, 2014).
mood disorder (3 papers, 2009 to 2025). A cognitive disorder a disturbance in which the person's mood is hypothesized to be the main underlying feature. "More recently, reductions in GLO1 mRNA in the blood of mood disorder patients have been reported; patients with the same diagnosis but in remission showed normal GLO1 mRNA levels, raising the possibility that mRNA for GLO1 is a state-dependent marker of certain affective disorders." (PMID 19266052, 2009).
neuroblastoma (3 papers, 2014 to 2020). Neuroblastoma (NB) is the most common solid, extracranial childhood tumor. "In another study, SH-SY5Y neuroblastoma cells were incubated SR (2.5 μM) and after 24 h and 48 h, the Glo1 activity increased significantly." (PMID 30445774, 2018). "The inhibition of Glo1 leads to enhanced MG levels and prolonged induction of caspase-3 activation and alterations in calcium homeostasis as shown in human neuroblastoma cells SH-SY5Y." (PMID 24498315, 2014). "An increase of Glo1 expression and activity was measured in SH-SY5Y neuroblastoma cells treated with SR at the same concentration (2.5 μM) and at the same times (24 h and 48 h)." (PMID 30445774, 2018).
oropharyngeal squamous cell carcinoma (3 papers, 2017 to 2023). "In addition, strong nuclear GLO-1 staining in vivo has also been significantly correlated with shorter progression-free and disease-specific survival and represents an independent risk factor for an unfavourable prognosis in oropharyngeal squamous cell carcinoma patients." (PMID 37299554, 2023). "In tumor cells of oropharyngeal squamous cell carcinoma (OPSCC), Glo1 expression is positively correlated to argypirimidine modification, and Glo1 protein levels are increased following exogenous MGO administration." (PMID 33869040, 2021).
osteoporosis (3 papers, 2014 to 2024). A condition of reduced bone mass, with decreased cortical thickness and a decrease in the number and size of the trabeculae of cancellous bone (but normal chemical composition), resulting in increased fracture incidence. "Several other genes such as TREML2, HTR1E, and GLO1 are shown to be novel susceptible genes for osteoporosis, as confirmed from other studies." (PMID 25364766, 2014). "Three shared genes (“TREML2,” “HTR1E,” and “GLO1”) may have important biological functions related to BMD associated with osteoporosis." (PMID 25364766, 2014). "In terms of bone and joint protection, the mechanisms of the protective effects on osteoporosis or osteoarticular disease involve regulation of the signaling of caspase-3/9, Bax/Bcl-2, PI3K/Akt/mTOR, Glo1-AGE-RAGE, AKT/Erk, and NF-κB signaling." (PMID 39301568, 2024).
restless legs syndrome (3 papers, 2012 to 2026). A condition that occurs while resting or lying in bed; it is characterized by an irresistible urgency to move the legs to obtain relief from a strange and uncomfortable sensation in the legs. "Multiple genome-wide association studies have implicated a haplotype block that includes GLO1 in restless legs syndrome." (PMID 23181072, 2012). "Moreover, the GLO1 gene is associated with restless legs syndrome, which is relatively common in patients receiving antipsychotics." (PMID 40826483, 2025).
triple-negative breast carcinoma (3 papers, 2014 to 2022). An invasive breast carcinoma which is negative for expression of estrogen receptor (ER), progesterone receptor (PR), and human epidermal growth factor receptor 2 (HER2). "Induced GLO1 expression as an adaptive response to elevated MG levels was reported previously for triple negative breast cancer cell lines." (PMID 28549423, 2017). "Accordingly, we found that MDA-MB-231 and MDA-MB-468 triple negative breast cancer cells adapted their level of Glo-1 expression and activity when treated with exogenous increasing doses of MG." (PMID 24978626, 2014). "Considering that MCF-7 cells remained stable for Glo-1 under the same conditions, it is tempting to speculate that triple negative breast cancer cells increased their Glo-1 activity as a control defense mechanism to prevent MG accumulation." (PMID 24978626, 2014). "The increase of Glo-1 activity may represent a strategy adopted by aggressive cancer cells such as triple negative breast cancer cells as a defense mechanism against the glycation damage induced by high intracellular MG accumulation." (PMID 24978626, 2014).
acute kidney injury (2 papers, 2016 to 2020). Sudden and sustained deterioration of the kidney function characterized by decreased glomerular filtration rate, increased serum creatinine or oliguria. "These glycolysis parameters (methylglyoxal, GLO1, and D-lactate) increased in the chronic AAN, which were quite different from acute kidney injury model." (PMID 31968011, 2020).
alcoholic (2 papers, 2019 to 2022). "Therefore, we reasoned that GLO1 SNPs contribute to the development of CP and investigated whether genetic variants in GLO1 are associated with alcoholic CP (ACP) or non-alcoholic CP (NACP)." (PMID 31661534, 2019).
Arthritis (2 papers, 2019 to 2025). Inflammation of a joint. "This is the first time that Glo-1 expression has been explored in cartilage, despite the speculated role of the Glo enzymatic system in arthritis proposed several years ago." (PMID 30635030, 2019).
Ascites (2 papers, 2022 to 2025). Accumulation of fluid in the peritoneal cavity (between the layers of the peritoneum that lines the abdomen). "The most important were stage (OR: 69; 95% CI 6.32-753.61), GLO1 mRNA overexpression (OR: 5.95; 95% CI 1.15-30.51), and ascites (OR: 2; 95% CI 0.49-8.32)." (PMID 35992817, 2022).
autism spectrum disorder (2 papers, 2017 to 2024). A spectrum of developmental disorders that includes autism, and Asperger syndrome. "Accumulating studies have shown an important role of Glo1 in regulating cortical development and neurogenesis, potentially contributing to the pathogenesis of autism spectrum disorder (ASD) when impaired." (PMID 39058101, 2024). "Emerging research discloses the relationship between Glo1 and autism spectrum disorder (ASD)." (PMID 39058101, 2024).
Cirrhosis (2 papers, 2017 to 2025). A chronic disorder of the liver in which liver tissue becomes scarred and is partially replaced by regenerative nodules and fibrotic tissue resulting in loss of liver function. "Downregulation of Glo1 (at mRNA and protein levels) positively correlated with the severity of cirrhosis, and associated with the increase in MGO, was reported both in the whole liver and liver cells obtained from cirrhotic animals." (PMID 40141037, 2025). "MGO and Glo1 have been implicated in the development of liver fibrosis and cirrhosis as shown in experiments on rats with induced cirrhosis as well as liver-derived cells in culture." (PMID 40141037, 2025). "However, the inhibition of Glo1 activity with the application of its inhibitors ameliorated cirrhosis features in animal livers, as well as reduced the activation of (LPS-induced) stellate cells in vitro." (PMID 40141037, 2025). "On the one hand, Glo1 expression decreases during the development of cirrhosis and leads to the elevation of MGO and further consequences yielding AGE formation and RAGE induction which triggers pro-oxidative and proinflammatory pathways through HSCs (and possibly Kupffer cells) activation." (PMID 40141037, 2025).
diabetic foot ulcers (2 papers, 2024 to 2025). "For instance, it has been shown the therapeutic potential of a biocompatible scaffold incorporating genes for both GLO-1 and β-klotho to reduce MG levels and reprogram diabetic adipose-derived stem cells (dADSCs) for the treatment of diabetic foot ulcers." (PMID 40727469, 2025). "In conclusion, this study shows that the dual GAS containing GLO-1 and β-klotho genes directed a more normalized dADSC response and may be beneficial in directing improved wound healing for diabetic foot ulcers." (PMID 38399319, 2024).
endometrial cancer (2 papers, 2022 to 2023). Primary or metastatic malignant neoplasm involving the endometrium (mucous membrane that lines the endometrial cavity). "This indicates that metformin can enhance sensitivity to chemotherapeutic drugs in endometrial cancer by downregulating Glo1 expression." (PMID 35898868, 2022). "According to the literature in the field of endometrial cancer, we found that metformin was an effective inhibitor of Glo1 that had antitumor activity, although the intrinsic mechanism needs to be explored further." (PMID 35898868, 2022). "Metformin sensitizes endometrial cancer cells even progestin-resistant EC cells to progestin by promoting progesterone receptor, downregulating glyoxalase I expression, downregulating glyoxalase I expression." (PMID 37415671, 2023). "This suggests that Glo1 is related to progestin resistance in endometrial cancer." (PMID 35898868, 2022). "Therefore, the combination of metformin and MPA is likely an effective strategy for conservative treatments of endometrial cancer and accumulating evidence suggests that Glo1 is a potential target gene of metformin." (PMID 35898868, 2022).
head and neck squamous cell carcinoma (2 papers, 2017 to 2018). A squamous cell carcinoma that arises from any of the following anatomic sites: lip and oral cavity, nasal cavity, paranasal sinuses, pharynx, larynx, and salivary glands. "So far, neither the expression of GLO1 nor its impact on malignant progression or prognosis have been addressed for head and neck squamous cell carcinoma (HNSCC)." (PMID 28549423, 2017).
hyperlipidaemia (2 papers, 2016 to 2025). "Hyperlipidemia, characterized by significantly elevated TG and VLDL levels, was observed in female Glo1+/− mice at 28 weeks compared to WT counterparts." (PMID 39896461, 2025).
Hypertension (2 papers, 2022 to 2023). The presence of chronic increased pressure in the systemic arterial system. "Mice presented with reduced GLO1 expression in basilar arteries, and this was negatively correlated with medial cross-sectional area and blood pressure in basilar arteries during hypertension." (PMID 35682865, 2022). "In GLO1-overexpressing mice, cerebrovascular remodelling in basilar artery tissue during Ang II-induced hypertension development was improved, pointing to a role of GLO1 (and thus MGO reduction) as a negative regulator of hypertension-induced cerebrovascular remodelling." (PMID 35682865, 2022). "Thus, increased levels of MGO and reduced Glo1 activity shown to play a role in hypertension." (PMID 37875994, 2023). "Moreover, it is important to address the role of hypertension and the consequence for BBB integrity because in angiotensin II mediated hypertension Glo1 protein expression was reduced in brain microvessels." (PMID 37875994, 2023). "By increasing Glo1 expression in vivo through viral transfection, VSMC proliferation was reduced and hypertension mediated cerebrovascular remodeling could be prevented." (PMID 37875994, 2023).
kidney cancer (2 papers, 2018 to 2025). Primary or metastatic malignant neoplasm involving the kidney. "However, although this study clearly demonstrated Glo1 involvement in kidney cancer, it identified some potential limitations, the most important of which was the lack of a biological link, since Glo1 activity was not measured either in tissue or blood samples." (PMID 29385039, 2018).
malaria (2 papers, 2021 to 2022). Malaria is a serious and sometimes fatal disease caused by a parasite that commonly infects a certain type of mosquito which feeds on humans. "The prospective treatment applications for Glo1 inhibitors are cancer chemotherapy, adjunct therapy of high Glo1-expressing, multidrug-resistant tumors, and malaria." (PMID 35269594, 2022).
metastatic disease (2 papers, 2017 to 2018). "GLO1 copy number was: primary tumour, 3.16 [2.37 – 4.61], metastatic tumour 3.63 [3.22 – 7.06], n = 18; Wilcoxon Signed Rank test, P>0.05." (PMID 29100361, 2017). "For tumours with metastases, GLO1 copy number was not changed between primary and metastatic tumours." (PMID 29100361, 2017). "For tumours with metastases, GLO1 copy number was not changed between primary and metastatic tumour: primary tumour, 3.00 [2.25 – 4.04]; metastatic tumour 3.55 [2.94 – 6.53], n = 19; Wilcoxon Signed Rank test." (PMID 29100361, 2017).
metastatic prostate carcinoma (2 papers, 2018 to 2025). A carcinoma that arises from the prostate gland and has spread to other anatomic sites. "In the context of metastatic prostate cancer, elevated GLO-1 expression can contribute to the establishment of an immunosuppressive microenvironment, promoting the upregulation of programmed death ligand 1 (PD-L1) expression, a process mediated by 5-hydro-5-methylimidazolone." (PMID 40727469, 2025).
monocytic leukemia (2 papers, 2016 to 2022). "We found that GLO1 is highly expressed in monocytic leukemia tumor cells in comparison to human PBMC as analyzed by enzyme activity measurement, Western blot and mRNA expression." (PMID 27579985, 2016).
non-alcoholic fatty liver disease (2 papers, 2022 to 2025). "In the liver, downregulation of GLO1 is associated with the development of non-alcoholic fatty liver disease in mice and humans." (PMID 36093169, 2022).
oligodendroglioma (2 papers, 2010 to 2018). A well-differentiated (WHO grade II), diffusely infiltrating neuroglial tumor, typically located in the cerebral hemispheres. "Higher expression of the enzyme glyoxalase I has been found in oligodendrogliomas with chromosome 1p intact compared to those with a deletion." (PMID 20454582, 2010). "This is consistent with our findings in oligodendrogliomas that GLO-1 expression is higher in malignancies with chromosome 1p intact." (PMID 20454582, 2010). "We previously demonstrated significantly higher expression of the enzyme glyoxalase I (GLO-1) in human oligodendroglioma tumor specimens with chromosome 1p intact compared to those with 1p losses." (PMID 20454582, 2010). "Interestingly, GLO-1 is located on chromosome 6, so the 1p loss in these chemosensitive oligodendrogliomas does not directly disrupt the GLO-1 gene." (PMID 20454582, 2010).
panic attacks (2 papers, 2012 to 2013). "A common Ala111Glu substitution in GLO1, responsible for conformational change and decreased enzymatic activity, was investigated in 162 panic disorder patients and 288 matched controls from the Italian population." (PMID 23659354, 2013). "Similarly, no published GWAS studies of panic disorder have identified GLO1." (PMID 23181072, 2012).
prostate (2 papers, 2017 to 2018). "In human urogenital cancer, GLO1 activity was decreased with subsequent increase in AGEs." (PMID 29321821, 2017).